IL7 (interleukin 7)
Diseases named in the same sentence as IL7 in open-access papers (continued):
Sharing a sentence is not in itself a finding about the gene and the disease.
nasal polyps (3 papers, 2021 to 2024). "Our findings suggest a close relationship between IL-6 and IL-7 in the epithelium as well as in the subepithelial connective tissue of nasal polyps." (PMID 36285981, 2022). "Ki-67 correlations with cytokines characterized previously established IL-4, IL-7, and IL-12 involvement in tissue proliferation in primary nasal polyps." (PMID 36285981, 2022). "When comparing nasal polyp samples with normal mucosa from control patients, it was apparent that IL-1α, IL-4, IL-6, IL-7, IL-8, IL-10, IL-12 positive structures were significantly decreased in epithelium of the polyps." (PMID 34208325, 2021). "IL-7 positive structures in nasal polyps were significantly decreased in epithelium (p < 0.001) and increased in the connective tissue (p = 0.006) in comparison to control samples." (PMID 34208325, 2021). "Due to its role in T and B cell development, IL-7 is worth examining in the tissue of nasal polyps." (PMID 36285981, 2022). "IL-4, IL-7, IL-10, and IL-12 correlate with Ki-67 which suggests the possible involvement of these cytokines in tissue cell proliferation in the case of recurrent nasal polyps." (PMID 36285981, 2022). "Decrease of IL-6 in both—epithelium and connective tissue with strong correlation between it and IL-7 and IL-10 in connective tissue suggests significant stimulation of this regulatory cytokine and, possibly, the important role in pathogenesis of the development in nasal polyps." (PMID 34208325, 2021). "IL-7 has not been used extensively in sample studies of CRS tissue and mostly was present in patients with nasal polyps." (PMID 34208325, 2021).
osteosarcoma (3 papers, 2023 to 2025). A usually aggressive malignant bone-forming mesenchymal neoplasm, predominantly affecting adolescents and young adults. "In conclusion, the co-expression of CXCR5 and IL-7 in NKG2D-CAR-T cells holds promise for optimizing CAR-T cell therapy for osteosarcoma." (PMID 39450160, 2024). "C5/IL7-CAR-T cells outperformed conventional CAR-T in eradicating osteosarcoma in mouse models and displayed better survival." (PMID 39450160, 2024). "Concomitantly, C5/IL7-CAR-T cells in the osteosarcoma microenvironment displayed low TIGIT expression and were able to express more IFN-γ in the NSG mouse model." (PMID 39450160, 2024). "The results signify that incorporating C5/IL7 enhances the cytotoxic potential of CAR-T cells against osteosarcoma cell lines." (PMID 39450160, 2024). "Given the high expression of MICA/B and CXCL13, human osteosarcoma cell lines constitute the perfect avenue for studying our CAR system expressing NKG2D, CXCR5, and IL-7." (PMID 39450160, 2024). "In one study, a CAR T cell co-expressing CXCR5 and IL-7 (C5/IL7-CAR-T) was designed to enhance the survival of CAR T cells and reduce cell depletion and apoptosis through the pSTAT5 signaling pathway, showing significant efficacy in the treatment of osteosarcoma." (PMID 40129944, 2025).
psoriatic arthritis (3 papers, 2014 to 2016). Joint inflammation associated with psoriasis. "Increased serum levels of many cytokines were indeed found in other rheumatic diseases: notably psoriatic arthritis (IL-6, IL-7, IL-10, and IFN-γ, TGF-β, or TNF-α) suggesting that such rises may reflect inflammation rather than being disease specific." (PMID 28057980, 2016).
pulmonary tuberculosis (3 papers, 2012 to 2025). A bacterial infection that affects the lungs and is caused by Mycobacterium tuberculosis. "It has a key role in T cell homeostasis with perturbation of the IL7/IL7 receptor axis occurring with advancing HIV but the biological role of IL7 in pulmonary tuberculosis is uncertain." (PMID 26567164, 2015). "In this study, we enrolled a group of pulmonary TB patients in eastern China and observed more severity in iron-deficient patients whose MAIT, Vδ2+, and Treg cells showed lower frequency in the periphery while IL-1β and IL-7 were higher." (PMID 39898042, 2025).
renal cell carcinoma (3 papers, 2014 to 2024). "For instance, in a clinical phase I study launched by Westermann and colleagues, they immunized renal cell cancer (RCC) patients with IL-7 and CD80 genes cotransfected RCC tumor cells cancer vaccine." (PMID 36389666, 2022). "A phase I study demonstrated safety of a vaccine against renal cell carcinoma (RCC) containing tumor cells expressing RCC26/IL-7/CD80; while they did not observe increased Th1 specific immune responses, they did find higher levels of Th2 mediated IL-10 expression in patients who responded." (PMID 25268164, 2014).
schizophrenia (3 papers, 2017 to 2023). A major psychotic disorder characterized by abnormalities in the perception or expression of reality. "Risperidone therapy led to an increase in IFN-α2, IL-1β and IL-7 in schizophrenia patients with MetS." (PMID 34065135, 2021).
Spondyloarthritis (3 papers, 2019 to 2023). "We further demonstrate that IL7R-expressing monocytes are responsive to IL-7 with a distinct expression profile that significantly overlaps ex-vivo IL7R+ monocytes from the joints of patients with spondyloarthropathies." (PMID 31594933, 2019). "Since the most well-known function of IL-7 is that of shaping and regulating CD8 cytotoxic T cells, the interesting possibility of its role in diseases associated with the major class I histocompatibility complex, such as spondyloarthritis (SpA), arises." (PMID 31276000, 2019).
T-cell leukemia (3 papers, 2020 to 2021). A malignant disease of the T-lymphocytes in the bone marrow, thymus, and/or blood. "Given the role of Notch in T-cell leukemogenesis and the converging effects of Notch and IL-7 on SKP2, we investigated the role of SKP2 in T-ALL leukemogenesis in vivo by using a Notch-induced T-cell leukemia mouse model." (PMID 31772299, 2020). "As a consequence, the overall structure remained intact and IL-7 cleaved by MMP-9 remained able to induce IL-7R internalization, to activate signal transduction through pSTAT3 and to induce cell proliferation in the human T cell leukemia cell line HPB-ALL." (PMID 34276694, 2021).
toxoplasmosis (3 papers, 2010 to 2022). A parasitic disease contracted by the ingestion or fetal transmission of toxoplasma gondii. "Apart from IL-7 and IL-15, potential role of other γc family members like IL-4 and IL-21 that have been implicated in CD8 memory generation in other infectious disease models, need to be considered in future investigations of memory CD8+ T cell development during toxoplasmosis." (PMID 20520779, 2010). "This suggests that absence of IL-15 or IL-7 alone does not affect CD8+ T cell activation during acute Toxoplasmosis." (PMID 20520779, 2010).
acute myeloid leukemia (2 papers, 2023 to 2024). Acute myeloid leukemia (AML) is a group of neoplasms arising from precursor cells committed to the myeloid cell-line differentiation. "We engineered T cells to constitutively secrete IL7 or to express an anti–acute myeloid leukemia–targeted IL7Rα–chimeric cytokine receptor (CCR) and characterized the phenotype of these cell types." (PMID 39186002, 2024).
adenoma (2 papers, 2015 to 2017). A neoplasm arising from the epithelium. "To resolve discrepancy between the reports, we investigated IL-7 in the context of adenomas, their number, size, and growth pattern." (PMID 27866242, 2017). "Patients with adenomas had higher IL-7 than controls and lower than patients with active IBD, whose cytokine levels were significantly more elevated than in any other group except for inactive disease." (PMID 27866242, 2017). "However, IL-7 was significantly higher in patients with adenomas displaying a villous growth pattern (villous adenomas and tubulovillous adenomas) as compared to tubular adenomas: 20.6 pg/ml (95% CI 12.9–32.7) and 9.2 pg/ml (7.2–11.8), p = 0.001." (PMID 27866242, 2017). "It allowed us to confirm significance of the elevation of IL-7 in CRC, adenoma, and IBD patients as compared to controls in age-matched analysis." (PMID 27866242, 2017). "Pairwise correlation analysis was used to determine if the expected relationships existed between cytokines assayed in this study in the IL-7 positive samples, which were used to assay if elevated cytokine profiles were observed in participants with adenomas relative to those without an adenoma." (PMID 25884547, 2015).
alopecia areata (2 papers, 2021 to 2023). Loss of scalp and body hair involving microscopically inflammatory patchy areas. "In a mouse model of alopecia areata, blockade of IL-7 signaling with anti-mouse IL-7Rα antibody suppressed inflammatory responses and reversed alopecia areata." (PMID 37881433, 2023).
alveolitis (2 papers, 2009 to 2024). "In comparison with alveolitis due to other diseases, SSc-related alveolitis was characterized by higher levels of IL-7, suggesting disease-specific pathogenic processes." (PMID 19615053, 2009).
Arthralgia (2 papers, 2009 to 2018). "Additionally, ZIKV-infected subjects with arthralgia showed higher levels of IL-1ra, whereas those with hyperemia showed lower plasma levels of IL-6, IL-7, and VEGF." (PMID 29774022, 2018). "The detection of IL-7 and IL-15 is significantly interesting with regards to the immunopathology of CHIKF since CHIKV infection has been shown to induce rapidly developing and persisting arthralgia." (PMID 19156204, 2009).
Atrophy (2 papers, 2024 to 2025). Any weakening or degeneration, especially through lack of use. "In addition to these effects, APOE-ε4 decreases plasma interleukin 7 (IL-7) levels and interleukin 7 receptor (IL-7R) signaling in in peripheral blood mononuclear cells, disrupting immune balance and enriching T cells, which may exacerbate neuroinflammation, hippocampal atrophy, and neuronal damage." (PMID 39858858, 2025).
bipolar disorder (2 papers, 2023 to 2024). A disorder of the brain that causes unusual shifts in mood, energy, activity levels and the ability to carry out day-to-day tasks. "A study of 42 adults with bipolar disorder found that IL-7 levels were significantly associated with measures of cognition, showing higher levels in the cognitively unimpaired group and a positive correlation with cognitive performance." (PMID 37287969, 2023).
brain tumors (2 papers, 2020 to 2023). "While there is limited research on local IL7 delivery in brain tumors, one study demonstrated that co-delivery of intravenous CAR T cells with intratumoral IL7-loaded oncolytic adenovirus increased survival in GBM xenografts." (PMID 36817432, 2023).
cognitive decline (2 papers, 2020 to 2022). "In C57BL/10 mice, PCR analysis revealed that the intrathymic IL-7 concentration was decreased in older animals, and this was correlated with cognitive decline." (PMID 36552799, 2022). "In turn, lower IL-7 has been correlated with cognitive decline during aging and a reduction in IL-7 in plasma previously observed in ME/CFS suggests a reduction in immune activation along with a potential neuropathology similar to the process of aging." (PMID 33046133, 2020).
colon adenocarcinoma (2 papers, 2014 to 2023). "The efficacy of the OXP plus IL-7 treatment against the highly invasive metastatic mouse CT26 colon adenocarcinoma was evaluated based on the rate of response in our experiment." (PMID 24465710, 2014).
colorectal tumors (2 papers, 2014 to 2019). "Mean IL-7 concentration in colorectal tumors was higher than in normal tissue: 88.6 pg/g (71.1–106) vs. 57.6 pg/g (41.8–73.5)." (PMID 31185636, 2019).
cystic fibrosis (2 papers, 2022 to 2025). Autosomal recessive disorder caused by pathogenic variants in the CFTR gene (cystic fibrosis transmembrane conductance regulator), which encodes a chloride and bicarbonate channel expressed in epithelial cells, and follow the diagnosis criteria. "The results indicated elevated serum IL-7 levels in cystic fibrosis patients that were correlated with chronic decline of lung function." (PMID 41305439, 2025).
diabetic retinopathy (2 papers, 2017 to 2023). "IL-6, IL-7, IL-8, IFN-γ and IP-10 were reported to be associated with inflammation in diabetic retinopathy, branch and central retinal vein occlusion and choroidal neovascularization." (PMID 28486560, 2017).
diffuse large B-cell lymphoma (2 papers, 2022 to 2024). "An animal experiment was conducted to investigate the efficacy of a long-acting genetically modified IL-7 in combination with CD19-targeted CAR-T cell therapy in mice with recurrent or refractory diffuse large B-cell lymphoma (DLBCL)." (PMID 38664743, 2024).
eating disorder (2 papers, 2016 to 2021). A broad group of psychological disorders with abnormal eating behaviors leading to physiological effects from overeating or insufficient food intake. "Overall, it is likely that extremes in BMI have a greater effect on many inflammatory markers (e.g., IL-7, IL-12/IL-23p40, IL-22) than comorbid psychiatric symptoms and/or eating disorder psychopathology." (PMID 34442458, 2021). "According to all those elements, this study was thus designed to explore IL-7 circadian plasma levels over 24 hours in eating disorder’s patients, CT, and healthy obese patients compared to a control group." (PMID 27611669, 2016). "The present study is the first published report evaluating IL-7 circadian profile in human in several categories of body weight and eating disorders." (PMID 27611669, 2016). "The present study is the first published report evaluating IL-7 circadian profile in humans in several categories of body weight and eating disorders." (PMID 27611669, 2016).
encephalitis (2 papers, 2019 to 2024). An acute inflammatory process affecting the brain parenchyma. "The relationship between IL-7 and LPTF-B1 and encephalitis involves complex immunoregulatory mechanisms." (PMID 40008261, 2024). "Through this study, it was confirmed that Caspase 8 levels, Interleukin-10 levels, Interleukin-7 levels, and TNF-beta have a positive correlation on the occurrence of viral encephalitis at the genetic level." (PMID 40008261, 2024).
endometrial cancer (2 papers, 2016 to 2024). Primary or metastatic malignant neoplasm involving the endometrium (mucous membrane that lines the endometrial cavity). "Given the scarcity of data on these proteins in endometrial cancer, this study aims to evaluate the diagnostic potential of preoperative serum concentrations of IL-4, IL-7, IL-9, IL-10, NT, TSP-2, and NRP1." (PMID 39334861, 2024). "Frequent mutations in PTEN (50%) and genes involved in the endometrial cancer-related molecular pathway including IL-7 signaling pathway." (PMID 27847479, 2016). "The limited research on IL-7 in endometrial cancer suggests a need to explore its role as a potential diagnostic marker." (PMID 39334861, 2024). "Although available studies on IL-7 in endometrial cancer are limited, the literature contains data on the assessment of this cytokine in other cancers." (PMID 39334861, 2024). "In our study, we observed elevated levels of IL-7 in the serum of patients with endometrial cancer compared with the control group." (PMID 39334861, 2024). "Our findings contribute to the growing body of evidence suggesting that IL-7 could be a useful biomarker for the diagnosis of endometrial cancer." (PMID 39334861, 2024). "Our study aimed to determine whether IL-4, IL-7, IL-9, IL-10, NT, TSP-2, and NRP1 could be diagnostic markers for endometrial cancer in women." (PMID 39334861, 2024). "IL-4, IL-7, IL-9, NT, and NRP1 may be useful diagnostic markers for endometrial cancer." (PMID 39334861, 2024). "This study suggests the clinical utility of IL-4, IL-7, IL-9, NT, and NRP1 in the diagnosis of endometrial cancer." (PMID 39334861, 2024). "The initial study presented here demonstrates the clinical utility of IL-4, IL-7, IL-9, NT, and NRP1 in endometrial cancer." (PMID 39334861, 2024). "The purpose of this study was to determine if IL-4, IL-7, IL-9, IL-10, NT, TSP-2, and NRP1 could be used as novel, helpful markers for the detection of endometrial cancer." (PMID 39334861, 2024). "Finally, we evaluated the significance of IL-4, IL-7, IL-9, IL-10, NT, TSP-2, and NRP1 in the diagnosis of endometrial cancer." (PMID 39334861, 2024).
endometriosis (2 papers, 2017 to 2024). The growth of functional endometrial tissue in anatomic sites outside the uterine body. "Several serum cytokines such as interleukins (IL) IL1β, IL-5, IL-6, IL-7 and IL-12 are involved, and their levels were found to be altered in endometriosis as compared to in healthy women." (PMID 39309679, 2024).
endothelial dysfunction (2 papers, 2020 to 2021). In vascular diseases, endothelial dysfunction is a systemic pathological state of the endothelium (the inner lining of blood vessels) and can be broadly defined as an imbalance between vasodilating and vasoconstricting substances produced by (or acting on) the endothelium. "IL-7R was expressed in vascular endothelial, and both recombinant IL-7 and EGF has shown therapeutic effect on endothelial dysfunction." (PMID 33119592, 2020).
enteritis (2 papers, 2018 to 2026). Inflammation of the small intestine. "Quantitative PCR analysis showed that CGA suppressed the expression of pro-inflammatory factors including interferon-γ (Ifn-γ), interleukin-7 (Il-7), tumor necrosis factor-α (Tnf-α), and upregulated the anti-inflammatory cytokines interleukin-10 (Il-10) in LPS-induced enteritis mice." (PMID 41788896, 2026). "Moreover, since IL7 promotes naive intestinal T-cell homing and IL7R indicates T cell development, IL7R, up-regulated in the early stages but down-regulated in the middle stages, which indicated the diminishing of enteritis." (PMID 30246797, 2018).
Fabry disease (2 papers, 2020 to 2022). Fabry disease (FD) is a progressive, inherited, multisystemic lysosomal storage disease characterized by specific neurological, cutaneous, renal, cardiovascular, cochleo-vestibular and cerebrovascular manifestations. "FGF2, VEGF-A, VEGF-C, and IL-7 have recently been described as a proteomic signature of Fabry disease." (PMID 35268324, 2022). "The increase in IL-7 level, observed in this study, may contribute to autophagy impairment and inflammation observed in Fabry disease." (PMID 32370284, 2020). "The results showed a clear elevation of FGF2 and IL-7 in Fabry disease compared to all other LDs." (PMID 32370284, 2020).
fibromyalgia (2 papers, 2021 to 2022). A chronic disorder of unknown etiology characterized by pain, stiffness, and tenderness in the muscles of neck, shoulders, back, hips, arms, and legs. "The top five proteins that distinguished fibromyalgia patients from plasma controls were in serum STAMBP, SIRT2, CD40, AXIN1 and IL-7 and in CSF (CCL19, CCL23, IL-18, CX3CL1, FGF19, CXCL10, CCL11)." (PMID 36327322, 2022).
gingivitis (2 papers, 2021 to 2024). A disorder involving inflammation of the gums; may affect surrounding and supporting structures of the teeth. "The present study uncovered that T2DM increased the level of IL-7 in GCF of patients with gingivitis, while the IL-4 level was decreased." (PMID 33417619, 2021). "In patients with gingivitis, levels of IL-1β, IL-6, IL-7, IL-13, IL-17, IL-21 and MIP-3α in gingival crevicular fluid in the Sg group were lower in comparison with the Dg group." (PMID 33417619, 2021). "Finally, gingivitis produced changes in saliva, with salivary levels of GM-CSF, IL-6, IL-7, IL-15, IP-10, KC-like, IL-10, IL-18, MCP1, TNFα being statistically significantly higher in the saliva of CG2 dogs compared to CG1." (PMID 38521919, 2024). "IL-1β, IL-6, IL-7, IL-13, IL-17, IL-21 and MIP-3α in GCF of T2DM patients with gingivitis were significantly downregulated by statins treatment." (PMID 33417619, 2021).